LGALS3 (galectin 3)
Diseases named in the same sentence as LGALS3 in open-access papers (continued):
Sharing a sentence is not in itself a finding about the gene and the disease.
ovarian carcinoma (49 papers, 2010 to 2025). A malignant neoplasm originating from the surface ovarian epithelium. "In this paper, we demonstrated that morin sensitizes TOV-21G (cisplatin-sensitive) and SK-OV-3 (cisplatin-resistant) ovarian cancer cells to cisplatin, what is associated with a decrease of the expression of galectin-3 (an anti-apoptotic protein)." (PMID 30267152, 2018). "Morin sensitizes TOV-21G and SK-OV-3 ovarian cancer cells to cisplatin, what is associated with a decrease of the expression of galectin-3." (PMID 30267152, 2018). "In ovarian cancer, galectin-3 increases drug resistance and is also associated with poor survival rates in ovarian cancer patients." (PMID 27626163, 2016). "Another top expressing marker gene, LGALS3 (logFC = 0.8) is associated with cell migration, proliferation, adhesion, and cell-cell interaction in tumor cells, and is implicated in tumor progression and chemo-resistance of epithelial ovarian cancer." (PMID 38328306, 2023). "Here, we investigated how Galectin-3 affects the interaction between natural killer (NK) cells and neutrophils in the tumor microenvironment of ovarian cancer." (PMID 39759523, 2024). "Studies using an ovarian cancer organ-on-a-chip model have shown that platelets interact with tumor cells through glycoprotein VI and tumor galectin-3 under shear stress." (PMID 39518024, 2024). "MiR-424-3p has been shown to sensitize ovarian cancer cells to cisplatin by decreasing the expression of the anti-apoptotic protein galectin-3." (PMID 37569592, 2023). "In human ovarian cancer on a chip model, Revacept treatment also inhibited galectin-3-GPVI-mediated platelet-cancer cell interactions and pro-inflammatory phenotype, thereby attenuating the invasive potential of cancer cells." (PMID 36873388, 2023). "In ovarian cancer, galectin-3 is a ligand of platelet GPVI, and this interaction regulates platelet-dependent tumor cell extravasation and pro-inflammatory signature in cancer cells." (PMID 36873388, 2023). "More recently, galectin-3 has also been proposed as a ligand of platelet GPVI on ovarian cancer cells." (PMID 36873388, 2023). "Increased expression of galectin-3 has also been detected in advanced stages in patients with ovarian cancer." (PMID 34290095, 2021). "For example, overexpression of galectin-3 increased tumor burden in A2780 ovarian cancer xenografted mice." (PMID 34290095, 2021). "One of the proteins, associated with poor survival rates as well as chemoresistance in ovarian cancer, is galectin-3." (PMID 30585294, 2019). "In this paper, we demonstrated that miR-424-3p mimic sensitizes TOV-21G (cisplatin-sensitive) and SK-OV-3 (cisplatin-resistant) ovarian cancer cells to cisplatin by decreasing the expression of galectin-3 (an anti-apoptotic protein)." (PMID 30585294, 2019). "To briefly summarize, we believe that we demonstrated the potential of miR-424-3p to sensitize of ovarian cancer cells to cisplatin by decreasing galectin-3 expression." (PMID 30585294, 2019). "In the present study, we, for the first time, demonstrate, that miR-424-3p mimic can suppress galectin-3 expression in ovarian cancer cells, and thus sensitize them to cisplatin." (PMID 30585294, 2019). "We performed a reverse transfection of miR-424-3p mimic into SK-OV-3 and TOV-21G ovarian cancer cells, followed by Real TimeTM RT-PCR analysis of the expression of miR-424-3p and galectin-3 mRNA as well as ELISA assay for galectin-3 protein level." (PMID 30585294, 2019). "MiR-424-3p mimic sensitizes SK-OV-3 and TOV-21G ovarian cancer cells to cisplatin by decreasing the expression of galectin-3." (PMID 30585294, 2019). "Galectin-3 can induce ovarian cancer cell survival and chemoresistance through activating TLR4 pathway." (PMID 29788922, 2018). "Up-regulation of galectin-3 has been noticed in many cancers (however, in some occurs down-regulation), including ovarian cancer." (PMID 30267152, 2018).
ovarian carcinoma (continued). "It is also well known that overexpression of galectin-3 in ovarian cancer is involved in drug resistance to cisplatin and paclitaxel." (PMID 30267152, 2018). "To determine the effect of galectin-3 on the sphere formation of ovarian cancer cells, we prepared galectin-3-depleted cells by treating galectin-3 specific shRNA in galectin-3 high-expressing SKOV3 and OVCAR429 cells." (PMID 27626163, 2016). "We monitored galectin-3 expression in ten different ovarian cancer cell lines using RT-PCR and western blot analysis." (PMID 27626163, 2016). "Silencing of galectin-3 decreased the migration and invasion of ovarian cancer cells, and overexpression of galectin-3 reversed these effects." (PMID 27626163, 2016). "We analyzed the expression level of galectin-3 in malignant tissues of ovarian cancer patients using TCGA public database." (PMID 27626163, 2016). "Increased expression of galectin-3 was detected in advanced stages, compared to stage 1 or 2 in ovarian cancer patients, suggesting that galectin-3 supports stemness of these cells." (PMID 27626163, 2016). "The expression of Hes1 and Hey1 also increased in galectin-3-overexpressing A2780 ovarian cancer cells." (PMID 27626163, 2016). "In this study, we determined the molecular mechanism by which galectin-3 increases the proliferation of ovarian cancer cells in vivo and in vitro." (PMID 27626163, 2016). "Galectin 3 (LGALS3) is over-expressed in ovarian cancer, and so a second protein inhibitor was constructed from the sugar-binding domain of LGALS3 (amino acids 117 to 244) attached to the same pFUSE backbone (117-244LGALS3pFUSE)." (PMID 25965947, 2015). "Although only 16 patients with ovarian cancer were included in the study the significant statistical differences in galectin-3 concentration between normal and cancer patients was observed." (PMID 23658855, 2010). "Together, this study suggests further investigation to evaluate if a Galectin-3-targeting therapy may be used in ovarian cancer." (PMID 39759523, 2024). "Furthermore, galectin-3 positively regulates Notch 1 signaling pathway in ovarian cancer cells and directly interacts with Notch 1 intracellular domain through its CRD." (PMID 36823664, 2023). "It has been suggested that galectin-3 expression in ovarian cancer probably depends on tumour- or tissue-specific factors that may modulate its levels, which requires further study." (PMID 37238197, 2023). "The results indicate that EMT in ovarian cancer cells promotes interactions between cancer cells and T cells through the LGALS3 - LAG3 axis, which could increase T cell exhaustion in infiltrated tumors, dampening antitumor immunity." (PMID 38086828, 2023). "Interestingly, a positive correlation between circulating galectin-3 levels and paclitaxel resistance was demonstrated in patients with ovarian cancer." (PMID 34572756, 2021). "We compared the parameters that govern cancer cell metastasis (ECM invasion, proliferation, cytokine profile, and transcriptional readouts) in OTME-Chips that were either composed of original ovarian cancer cells (OTME-Chip) or galectin-3 knocked down cancer cells (KO–OTME-Chip)." (PMID 34290095, 2021). "Furthermore, since platelets have been shown to promote tumor chemoresistance, we examined the effect of GPVI–galectin-3 interaction and blocking this interaction by Revacept on chemoresistance in ovarian cancer cells." (PMID 34290095, 2021). "Thereafter, to evaluate platelet GPVI binding with tumor galectin-3, immediately after exposing the platelets to shear within the OTME-Chip and extravasation, we isolated and purified the GPVI protein from the platelets and galectin-3 from the ovarian cancer cells." (PMID 34290095, 2021). "We then investigated the possibility that the GPVI–galectin-3 interaction may serve as a mediator for platelet-promoted tumor metastasis in ovarian cancer." (PMID 34290095, 2021).
ovarian carcinoma (continued). "To test this hypothesis, we established an ovarian cancer cell line with galectin-3 knocked out (KO-g3) using the CRISPR-Cas9 editing method." (PMID 34290095, 2021). "Assessment of miR-424-3p mimic capability to sensitize SK-OV-3 and TOV-21G ovarian cancer cells to cisplatin by decreasing the expression of galectin-3, which is an anti-apoptotic protein overexpressed in ovarian cancer and associated with resistance to chemotherapy." (PMID 30585294, 2019). "An interesting potential target for miRNAs could be galectin-3, since it is an anti-apoptotic protein that is overexpressed in various tumor cells (including ovarian cancer) and involved in their chemoresistance." (PMID 30585294, 2019). "Furthermore, up-regulation of galectin-3 in various cancer cells (including ovarian cancer) makes them resistant to chemotherapeutic treatment." (PMID 30267152, 2018). "Taken together, our results suggested that galectin-3 played an oncogenic role in colorectal cancer, ovarian cancer and non-small cell lung cancer, indicating it could be a promising biomarker and a novel therapeutic target for them." (PMID 30410421, 2018). "Overexpression of galectin-3 increased tumor burden in A2780 ovarian cancer xenografted mice." (PMID 27626163, 2016). "We next determined how galectin-3 regulates Notch signaling in ovarian cancer cells." (PMID 27626163, 2016). "Based on these results, we suggest that targeting galectin-3 may be a potent approach for improving ovarian cancer therapy." (PMID 27626163, 2016). "Interestingly, depletion of galectin-3 significantly reduced spheroid formation, drug resistance and ovarian cancer cell motility." (PMID 27626163, 2016). "It strongly supports that galectin-3 promotes the malignancy of ovarian cancer." (PMID 27626163, 2016). "We were interested that galectin-3 regulates the Notch1 signaling pathway in ovarian cancer stem cells because Notch pathway genes might be important therapeutic targets for CSCs and many new agents targeting the Notch pathways have entered clinical trials." (PMID 27626163, 2016). "Therefore, we asked whether other tumor entities such as ovarian cancer cells have the same capacity, and whether Vδ1 T-cell proliferation is influenced by galectin-3." (PMID 38259448, 2023). "In view of the fact that morin is a known inhibitor of NF-κB, which in turn may influence the expression of galectin-3 (the anti-apoptotic protein), we hypothesized that morin will sensitize ovarian cancer cells to cisplatin, what will be achieved by reducing the expression of galectin-3." (PMID 30267152, 2018). "Moreover, inhibition of galectin-3 by MCP sensitizes SK-OV-3 ovarian cancer cells to paclitaxel." (PMID 30267152, 2018). "This study aimed at evaluating whether morin (a natural flavonoid and a known inhibitor of NF-κB) can sensitize ovarian cancer cells to cisplatin by decreasing the expression of galectin-3, which is an anti-apoptotic protein regulated by NF-κB transcription factor." (PMID 30267152, 2018). "Therefore, we strongly suggest that galectin-3 may be a potent target for regulating Notch1 signaling in ovarian cancer therapeutic strategies." (PMID 27626163, 2016). "Our results suggest that galectin-3 may be a potent target for ovarian cancer therapy." (PMID 27626163, 2016). "The expression of LGALS3 might be affected by the stage of ovarian cancer." (PMID 20969748, 2010). "MCP inhibits STAT3 phosphorylation and galectin-3, suppressing M2 macrophages and STAT3 signaling in breast, prostate, and ovarian cancers." (PMID 41346617, 2025). "We confirmed that PBMC and tumor cells released small amounts of galectin-3, which were significantly increased when coculturing PBMC with ovarian cancer cell lines (KI-OCp1 and 15, BG-1 and SKOV-3) in the presence of zoledronate after 72 hours." (PMID 38259448, 2023). "LGALS1, LGALS3, LGALS4, LGALS8 and LGALS9 were found to be overexpressed in ovarian cancer patients." (PMID 37238197, 2023).
ovarian carcinoma (continued). "Second of all, we evaluated the effect of miR-424-3p mimic on the expression of galectin-3 in SK-OV-3 and TOV-21G ovarian cancer cells." (PMID 30585294, 2019). "Not only in SKOV3 cells, we also determined the effect of galectin-3 on NICD1 formation in SNU-840, DOV13 and RMUG-1 ovarian cancer cells." (PMID 27626163, 2016). "Taken together, we conclude from this study that galectin-3 interacts with NICD1 and increases its cleavage and nuclear localization to support ovarian cancer stemness." (PMID 27626163, 2016). "Galectin-1 and galectin-3 are both up-regulated in among others bladder carcinoma, head and neck squamous cell carcinoma (HNSCC) and ovarian cancer." (PMID 24658839, 2014). "Galectin-3 can be a tool to distinguish the proactive and active forms of MMP-2 and -9 and galectin-4 as a marker of MOC in ovarian cancer." (PMID 23658855, 2010). "Additionally, RSV decreases galectin-3 (GAL-3) levels by raising miR-424-3p, thereby inhibiting glycolysis and targeting the AMPK/mTOR signaling pathway to suppress ovarian cancer cell proliferation and induce apoptosis." (PMID 39439517, 2024). "Further, the different galectin-3 concentrations did not influence the γδ T-cell-mediated cytotoxicity towards the ovarian cancer cells after 24 hours or after earlier time points." (PMID 38259448, 2023). "After expansion, Vδ1 T cells cocultured with ovarian cancer cells exert a high cytotoxicity which was not influenced by galectin-3 release of tumor cells." (PMID 38259448, 2023). "Using CRISPR-Cas9 knockout (KO) cancer cells, our platform revealed that platelets might promote ovarian cancer metastasis and chemoresistance through a shear-dependent interaction of their GPVI with galectin-3 expressed on the cancer cells." (PMID 34290095, 2021). "We demonstrated that miR-424-3p mimic effectively transfects into SK-OV-3 and TOV-21G ovarian cancer cells in which it significantly suppresses the expression of galectin-3 at the protein level, but not at the mRNA level." (PMID 30585294, 2019). "To investigate the effect of miR-424-3p on the expression of galectin-3, we performed Real TimeTM RT-PCR analysis and ELISA assay on the RNA and protein extracts obtained from SK-OV-3 and TOV-21G ovarian cancer cells, which we had previously transfected with miR-424-3p mimic." (PMID 30585294, 2019). "In contrast, Galectin-3 (Gal-3) expression level was not affected by the inhibition of the NF-κB pathway in ovarian cancer cells." (PMID 29738493, 2018). "High cytoplasmic Galectin-3 expression has been suggested as a negative prognostic factor, as it was shown to correlate with shorter progression-free survival in ovarian cancer." (PMID 28594391, 2017). "To determine how galectin-3 could regulate the stemness phenotype of ovarian cancer cells, we measured the mRNA expression of Notch, WNT/β-catenin, and SHH signaling pathway related genes in galectin-3-depleted SKOV3 cells." (PMID 27626163, 2016). "Overexpression of galectin-3 increased the motility of A2780 and OVCAR3 ovarian cancer cells." (PMID 27626163, 2016). "Besides, the addition of different concentrations of TD-139, a potent small-molecule inhibitor of galectin-3, did not improve γδ T-cell cytotoxicity against ovarian cancer cells after 24 hours or at earlier time points." (PMID 38259448, 2023). "The LGALS3 inhibitor GB0139 has shown promise in acute lung injury where its mechanism of action involves reducing IL-6, TNF-α, and MIP-1α69, and thus may also prove efficacious in ovarian cancer where TNF-α plays a role in EMT initiation and maintenance." (PMID 38086828, 2023).
colorectal cancer (48 papers, 2007 to 2026). A primary or metastatic malignant neoplasm that affects the colon or rectum. "The protein Galactin-3 is encoded by LGALS3 and altered expression of galectins in human gastrointestinal tissues as being implicated in colorectal cancer progression." (PMID 29934517, 2018). "The deletion of galectin-3-encoding gene sensitizes human keratinocytes, colorectal cancer cells, leukemia cells, human renal cell carcinoma and cholangyocarcinoma cells to apoptosis, whereas the overexpression of Lgals3 protects the cells from apotosis." (PMID 30800112, 2019). "Elevated LGALS3 expression has been reported in a variety of malignancies, including glioblastoma, breast cancer, melanoma, colorectal cancer, hepatocellular carcinoma, and pancreatic ductal adenocarcinoma." (PMID 41153387, 2025). "Galectin-3 is also highly abundant in stool, and fecal galectin-3 levels were increased in colorectal carcinoma patients with advanced tumor node metastasis (TNM) score, higher nuclear grade, poor tumor tissue differentiation and metastatic disease." (PMID 37189804, 2023). "As expected that expression of β3GnT2 also significantly elevated the mRNA levels of CD147, galectin 3, and MMPs in colorectal cancer cells in comparison with the controls." (PMID 29875690, 2018). "The localization of galectin-3 in normal cells and different stages of cancer cells were further investigated in cases of colorectal cancer progression." (PMID 29389859, 2018). "In the subgroup analysis of specific cancer type, we found that high expression of galectin-3 was correlated with shorter DFS/RFS/PFS in colorectal cancer (pooled HR = 2.49, 95% CI 1.82–3.41, I2 = 0.0%, p = 0.738)." (PMID 30410421, 2018). "For example, increased levels of galectin-3 are involved in liver metastasis, venous invasion and lymph node metastasis of colorectal cancer." (PMID 29389859, 2018). "Several studies disclosed that the over-expression of galectin-3 is closely related to the development of many human tumors, such as large-cell lymphoma, colorectal cancer, breast cancer, liver cancer, brain tumors, melanoma and thyroid cancer." (PMID 28355349, 2017). "Collectively, in our present study, we extend the knowledge on Galectin-3 by highlighting its role in colorectal cancer progression." (PMID 28146425, 2017). "Our findings suggest miR-128/Galectin-3 axis can be a biomarker for colorectal cancer and a candidate molecular target to improve the efficacy of colorectal cancer treatment." (PMID 28146425, 2017). "It has also been shown that galectin-3 is detected in gastric adenocarcinoma, colorectal cancer and other cancers." (PMID 28355349, 2017). "In this study, we demonstrated that extracellular CEA interacted with galectin-3 and promoted migration of colorectal cancer cells and distal metastasis." (PMID 28977916, 2017). "Here we demonstrated that Galectin-3 protein level was frequently up-regulated in colorectal cancer (CRC) cells and tissues." (PMID 28146425, 2017). "Four galectins, galectin-1, galectin-3, galectin-4, and galectin-8, are expressed in the human colon and rectum and their expressions show significant changes during colorectal cancer development and metastasis." (PMID 26448934, 2015). "We plan to measure the serum levels of galectin-1, galectin-3, and 90K/Mac-2BP of patients at different stages of colorectal cancer and analyze the correlation of these galectins with stages of colorectal cancers." (PMID 26448934, 2015). "Galectin-3 overexpression was observed in colorectal carcinoma, corresponding to a positive correlation with cancer progression and metastasis." (PMID 24303084, 2013). "Pre-treatment of HT29-5F7 cells with recombinant galectin-3 at similar circulating galectin-3 concentrations found in the sera of colorectal cancer patients resulted in a dose-dependent increase of HT29-5F7 but not HT29 cell aggregation." (PMID 20565834, 2010).